OR13J1 (olfactory receptor family 13 subfamily J member 1)
Description:
Odorant receptor.
Synonyms: OR9-2
Tractability: Small molecule: it belongs to a druggable protein family. Antibody: UniProt places it where antibodies can reach, with medium confidence; UniProt predicts a signal peptide or a membrane-spanning region; its Gene Ontology location is reachable by antibodies, with medium confidence.
Gene: Protein-coding gene on chromosome 9 (35,869,463 to 35,870,401, reverse strand). Ensembl gene ENSG00000168828.
Subcellular location: Cell membrane
Pathways (Reactome):
Sensory Perception: Expression and translocation of olfactory receptors
Gene Ontology:
Molecular function: olfactory receptor activity; G protein-coupled receptor activity
Biological process: detection of chemical stimulus involved in sensory perception of smell; G protein-coupled receptor signaling pathway
Cellular component: plasma membrane; membrane
Genetic constraint (gnomAD): Loss-of-function variants: 17 observed, 14.01 expected, observed/expected ratio (o/e) 1.21, 90% interval 0.83 to 1.76. The upper end of that interval is the gene's LOEUF score, 1.76, which puts it in group 6 of 6, group 1 being the genes least tolerant of losing a copy. Missense variants: 382 observed, 415.69 expected, observed/expected ratio (o/e) 0.92, 90% interval 0.84 to 1. Synonymous variants: 175 observed, 190.36 expected, observed/expected ratio (o/e) 0.92, 90% interval 0.81 to 1.04.
Homologues: Orthologues: chimpanzee OR13J1 (98% identical), macaque OR13J1 (88% identical), dog OR13J1 (84% identical), guinea pig OR13J1 (83% identical), mouse Or13j1 (82% identical), rat Or13j1 (82% identical), rabbit OR13J1 (81% identical). Paralogues in human: OR2K2 (52% identical), OR13C9 (52% identical), OR13C2 (51% identical), OR13D1 (51% identical), OR13C5 (50% identical), OR2S2 (50% identical), OR13C4 (50% identical), OR13C3 (49% identical), OR13C8 (48% identical), OR5V1 (46% identical), OR10C1 (45% identical), OR2D2 (44% identical), and 80 more.
Diseases named in the same sentence as OR13J1 in open-access papers:
OR13J1 is named in the same sentence as 3 diseases in open-access papers, as found by Europe PMC text mining. Sharing a sentence is not in itself a finding about the gene and the disease. The quoted sentences say what the papers report.
adenocarcinoma (1 paper, 2013). A common cancer characterized by the presence of malignant glandular cells. "Multiple genes involved in olfactory transduction and neuroactive ligand-receptor interaction including OR13J1, OR51E2, GNAL, and GRIK1 were also found by this study to be mutated in the adenocarcinoma, suggesting these two classes of genes warrant further investigation." (PMID 23301059, 2013).
OR13J1 also shares sentences with these, for which no sentence is quoted: colorectal adenoma (1 paper); tumor (1).